INS (insulin)
Diseases named in the same sentence as INS in open-access papers (continued):
Sharing a sentence is not in itself a finding about the gene and the disease.
Hypoglycemia (continued). "Administering insulin can improve lean body mass, bone mineral density, donor site healing, and decrease overall LOS in patients with severe burned injuries, although careful monitoring is required to avoid hypoglycemia." (PMID 39617150, 2025). "As she never developed significant hypoglycemia, a critical sample (including insulin and cortisol) was not obtained, and she was never started on diazoxide." (PMID 40605820, 2025). "The reports guided questioning, which revealed the patient was not aware that correction of hypoglycemia before administering insulin for his meals is necessary." (PMID 40142601, 2025). "An inpatient laboratory assessment ruled out insulinoma, as insulin and C‐peptide levels were not elevated in the context of spontaneous hypoglycemia." (PMID 40697895, 2025). "Among insulin-naive patients, once-weekly efsitora alfa achieved excellent glycemic control similar to degludec, with no concerning hypoglycemia or other safety findings." (PMID 39810242, 2025). "Since then, the patient has continued insulin therapy with the DiaPort System and has maintained good glucose control, with no severe hypoglycemia, a more controlled glucose variability, and a greater satisfaction compared to SC insulin therapy." (PMID 40995084, 2025). "The addition of GLP-1RA on top of insulin therapy in people with T1D results in a modest reduction in HbA1c, body weight, and TID without increasing the risk for severe hypoglycemia." (PMID 40760325, 2025). "In particular, several large randomized controlled studies showed that tight glycemic control using insulin does not result in improved mortality but rather increases the likelihood of inducing hypoglycemia in this patient population." (PMID 39753379, 2025). "Despite the established role of GCs in suppressing insulin secretion, we did not detect any changes in insulin levels during infection or following GR deletion, indicating that severe hypoglycemia in infected GRiKO mice occurs independently of insulin." (PMID 40702267, 2025). "Infants who received insulin treatment prior to 36 weeks PMA spent significantly longer time in hypoglycemia at 36 weeks PMA than infants who did not receive insulin treatment." (PMID 40576801, 2025). "Ultra-rapid-acting insulin did not significantly influence psychological outcomes as measured by the Hypoglycemia Fear Scale [MD 0.11, 95% CI [-3.68 to 3.89], P = 0.96, I2 = 0%]." (PMID 40547532, 2025). "The patient reported no prior or current usage of insulin or sulfonylurea, excluding the likelihood of iatrogenic hypoglycemia." (PMID 41333493, 2025). "Despite the proven efficacy of these drugs in reducing the risk of diabetic complications, their use is not without significant side effects, including hypoglycemia, particularly with insulin, and weight gain with SU." (PMID 40671916, 2025). "The oral and intravenous administration of insulin are not viable for clinical use due to issues of poor absorption and hypoglycemia, respectively." (PMID 40699683, 2025). "LEAP-2 analog blunts glucose peaks without hypoglycemia (early human); duodenal sleeve improves 2 h glucose/insulin responses (pilot human; DIO-rat support)." (PMID 41235333, 2025). "One case, a 71-year-old man receiving insulin, metformin, and a GLP-1 receptor agonist while on steroid replacement therapy for adrenal insufficiency, required discontinuation due to early-morning hypoglycemia." (PMID 41476904, 2025). "In pregnant women, hypoglycaemia (IC025 = 4.25) was detected as a strong signal, hypoglycaemia neonatal (IC025 = 2.96) as a medium signal, while ketoacidosis (IC025 = 0.76), decreased insulin requirement (IC025 = 0.24), and underweight (IC025 = 0.09) were identified as weak signals." (PMID 40997126, 2025). "In such a situation of marked hypoglycemia, an individual without endogenous hyperinsulinism should have suppressed insulin secretion." (PMID 40161293, 2025).
Hypoglycemia (continued). "It is generally characterized by reactive and persistent hypoglycemia in patients who have never received exogenous insulin and without pathological abnormalities in the pancreatic islets." (PMID 40584814, 2025). "The AMPLITUDE-L and AMPLITUDE-S studies also reported significant reductions in HbA1c, FPG, and body weight compared with those of the placebo, with low rates of hypoglycemia, particularly in patients not using insulin or sulfonylureas." (PMID 39917155, 2025). "Reported adverse events included extremity pain, hypoglycemia, diabetic ketoacidosis (in a patient with non-adherence to insulin), pancreatitis (in a patient with a history of the condition), and urogenital fungal infections." (PMID 40452043, 2025). "Noteworthy, the patient did not have a history of gastric bypass surgery in the past and there was no family history of hypoglycemia, personal history of diabetes, or exposure to insulin products." (PMID 39968421, 2025). "The phenotype reflects a lowered set point for insulin release, rather than tumoral secretion, with mild hypoglycemia managed with diet and glucometer usage." (PMID 41281935, 2025). "Although oral insulin and GLP-1RAs remain one of the great challenges facing the pharmaceutical industry, it is considered a safer and more convenient method for the management of hypoglycemia." (PMID 40006605, 2025). "Skewed insulin dosing remains possible due to various factors influencing blood glucose, and insulin dosing is unlikely to completely eliminate hypoglycemia." (PMID 40919135, 2025). "We next investigated whether inhibition of specific serotonin receptor subtypes could block serotonin-induced hypoglycemia, selecting inhibitors of 5-HTR3 and 5-HTR2, given their demonstrated role in metabolism and insulin secretion." (PMID 39264731, 2024). "The spontaneous dissociation of insulin from the insulin-IAA complexes does not cease when plasma glucose concentrations decrease, resulting in more unbound insulin, which further causes hypoglycemia." (PMID 39347250, 2024). "When liraglutide was used in place of a placebo, the incidence of severe hypoglycemia did not rise, indicating that the medication is safe when used with less insulin." (PMID 39273299, 2024). "No patients had acute or persisting sequelae requiring hospitalization from either the insulin‐induced hypoglycemia or fluorouracil and cyclophosphamide treatments nor were there any adverse events that necessitated admission of IV glucose to halt treatment." (PMID 39629677, 2024). "The rate of patients that achieved an HbA1c < 7.0% without developing clinically significant or severe hypoglycemia events at week 26 were higher in patients receiving insulin icodec rather than the control (52.1% vs. 39.1%)." (PMID 38610878, 2024). "For example, diabetic individuals with no optimal blood glucose control or using insulin/insulin secretagogues should be adequately hydrated and closely monitored pre and during exercise for ketosis and hypoglycemia, consequently." (PMID 38818165, 2024). "At 24 months, the group receiving alefacept had lower insulin requirements and 50% fewer episodes of hypoglycemia, however no meaningful differences in glycemia emerged." (PMID 39568817, 2024). "The patient on insulin detemir experienced hypoglycemia and was not on any other antidiabetic medications such as thiazolidinediones or sulfonylureas." (PMID 39211672, 2024). "Given that no patients at the hospital had hypoglycemia during the study, this intervention appears to be helpful for patients on insulin therapy who fear hypoglycemia." (PMID 39057524, 2024). "It has been reported that insulin-induced hypoglycemia increases the secretion of cortisol, but it does not affect plasma AVP levels." (PMID 39000501, 2024). "Tumours producing hypoglycaemia are classified into insulin-producing tumours and less common non-islet cell tumours." (PMID 39651031, 2024).
Hypoglycemia (continued). "Once the infant is born, these high insulin concentrations, in the absence of an adequate glucose supply, can lead to hypoglycaemia." (PMID 38872105, 2024). "In contrast, grafts from the C3H mice with rejection and the C3H mice presensitized with C57BL/6 spleen cells showed very few insulin-positive cells and lacked hypoglycemia and persistent bioluminescence signals." (PMID 38920672, 2024). "Last but not least, Insulin used in the form of medium- or long-acting analogs corrects blood sugar, reduces glucosuria and can induce hypoglycemia or weight gain." (PMID 39723164, 2024). "In other studies following RYGB individuals with post-RYGB hypoglycaemia had greater postprandial GLP-1 and insulin concentrations but not GIP when compared with individuals who had the same bariatric surgery but did not develop hypoglycaemia." (PMID 38546831, 2024). "The adjustments made to the systems to avoid hypoglycemia may have impacted the significant increase in TAR2, such as reducing the bolus with a 20% increase in carbohydrate grams per insulin unit at dinner." (PMID 39064653, 2024). "These aberrant cells can synthesize and secrete insulin independently, without the typical suppressive influence of hypoglycemia." (PMID 39595353, 2024). "In small case series of people with PBH, treatment with the GLP-1 analogue liraglutide improved symptoms of hypoglycaemia, fasting and post-prandial glucose concentrations, lowered insulin levels during an OGTT and in one case reduced time in hypoglycaemia on CGM." (PMID 38451861, 2024). "Similar to our findings, various studies in rats, mice, and humans all demonstrate that the intranasal insulin does not induce systemic hypoglycemia." (PMID 38235171, 2024). "The authors reported long-lasting biochemical and clinical improvement in hypoglycemia incidents and lowered serum insulin levels, and did not observe side effects at the five-month follow-up." (PMID 39057179, 2024). "The cohorts were poorly characterized in all insulin bolus calculator and noninvasive hypoglycemia detection studies, receiving only “no” ratings (Fisher exact test; P=.03)." (PMID 38241075, 2024). "The aim of allogenic transplantation is currently not to achieve an insulin-free status but to avoid severe hypoglycemia and maintain excellent blood glucose levels." (PMID 38786050, 2024). "The original generation of an insulin pump was sensor-augmented pump; the pumps had an insulin shutoff feature that activated when the user did not react to a hypoglycemia warning." (PMID 39065641, 2024). "We show that insulin-evoked hypoglycemia is severely aggravated in mice lacking the cation channel proteins TRPC1, TRPC4, TRPC5, and TRPC6, which cannot be explained by alterations in glucagon or glucocorticoid action." (PMID 39375537, 2024). "In this case, plasma insulin, pro-insulin, and C-peptide levels were in normal ranges during episodes of hypoglycemia and food restriction, indicating no participation of an insulinoma." (PMID 41542255, 2024). "The recent introduction of automated insulin delivery (AID) systems represents a game changer in T1D management, offering notably improved performances on glycemic control compared to other treatment modalities and protection against hypoglycemia." (PMID 39334618, 2024). "Furthermore, the potential for hypoglycemia emerges, particularly when SGLT2 inhibitors are co-administered with insulin secretagogues and insulin." (PMID 38694659, 2024). "The patient’s low insulin, C-peptide, and β-hydroxybutyrate levels during an episode of hypoglycemia indicated a noninsulin mediated process." (PMID 39372824, 2024). "Negative results for circulating oral hypoglycemic agents and insulin antibodies effectively ruled out oral hypoglycemic agent-induced hypoglycemia and insulin autoimmune hypoglycemia." (PMID 39125476, 2024). "Hypoglycemia is common in diabetic populations using insulin or insulin secretagogues, but rare in non-diabetics." (PMID 38629013, 2024).
Hypoglycemia (continued). "Blood glucose and insulin were within the normal range and there were no clinical symptoms of hypoglycemia." (PMID 39057179, 2024). "The commonly cited reasons for the switch from previous BIs were lack of efficacy and hypoglycemia concerns, which would be indicative of these two being the most important guiding factors behind the decision about which insulin to initiate." (PMID 36896906, 2024). "During his hospitalization, the patient presented episodes of hypoglycemia and spontaneous decreases in glucose levels, particularly just before the morning hydrocortisone dose even in the absence of basal insulin administration." (PMID 39091607, 2024). "Rates of combined level 2 or 3 hypoglycemia were significantly higher for once-weekly insulin icodec rather than once-daily degludec: 19.93 events per PYE vs. 10.37 events per PYE, respectively (estimated rate ratio = 1.9; 95% CI: 1.5 to 2.3)." (PMID 38610878, 2024). "Upon endocrinological assessment at admission, a lab assessment including tumor markers, revealed no abnormalities other than hypoglycemia (2.04 mmol/L) and suppressed serum insulin (<0.2 mU/L) and C-peptide (0.08 ng/ml) but no anti-insulin antibodies." (PMID 39435031, 2024). "Consistent with the phenotypes observed in the Ocn-Cre;Vhlflox/flox mice, the Dmp-1-Cre;Vhlflox/flox mice also had a lean appearance, hypoglycemia, and improved glucose tolerance, without any changes in serum insulin levels or pancreatic β cells." (PMID 38945950, 2024). "The most substantial advantage of intranasal insulin treatment tested in the current project is the absence of significant hypoglycemia, even at a high dose." (PMID 38235171, 2024). "Our study also showed that a history of myocardial infarction is associated with hypoglycemia during HHC, independently of the insulin dose received (data not shown)." (PMID 38594758, 2024). "The diagnosis of insulinoma is established by demonstrating inappropriately high serum insulin, C-peptide, and proinsulin concentrations without evidence of sulfonylurea use during a spontaneous or provoked episode of hypoglycemia." (PMID 39125476, 2024). "At the very beginning of PA, hypoglycaemia can occur via the activation of α-adrenergic autonomic afferent pancreatic fibres, a condition known as hypoglycaemia-associated autonomic failure (HAAF) irrespective of the reduction of basal insulin infusion rates." (PMID 38542818, 2024). "The test consists of a 72 h supervised fast in an inpatient setting with ongoing monitoring of plasma glucose, insulin, and C-peptide levels with or without beta-hydroxybutyrate until hypoglycemia occurs." (PMID 39330031, 2024). "Children with positive screening were found to be shorter and had significantly higher insulin doses, more hypoglycemia attacks, and recurrent DKA compared to negative cases." (PMID 38317100, 2024). "Hypoglycemic agents (e.g. insulin and insulin secretagogues) are not routinely indicated as they can precipitate hypoglycemia." (PMID 38556561, 2024). "In dogs that developed hypoglycemia after MVR, plasma glucagon levels were higher and serum insulin levels were lower than the preoperative levels, indicating that the cause of postoperative hypoglycemia did not appear to be hyperinsulinemia or hypoglucagonemia." (PMID 38393097, 2024). "They found a slightly higher risk of overall hypoglycemia and weight gain, without any difference in severe hypoglycemia with once-weekly basal insulin Icodec." (PMID 39861067, 2024). "Second, we could not gather detailed anthropometric data, such as body mass index and immunoreactive insulin, which could have helped to better understand the effect of these factors on HVHD/iatrogenic hypoglycaemia." (PMID 38975379, 2024). "The independence of the test and training samples was not demonstrated in studies focusing on insulin bolus calculation or hypoglycemia detection from CGM data." (PMID 38241075, 2024).
Hypoglycemia (continued). "The insulin challenge dose was 12 U/kg, which was higher than the 3 U/kg dose used in the PRL-2903 experiment, selected with the intent to induce level 2 hypoglycemia (<3.0 mmol/L) in the control group, whereas level 1 hypoglycemia (3.5 mmol/L blood glucose) was achieved in the PRL-2903 study." (PMID 38510652, 2024). "Further testing after 9 hours of fasting at her 4 months postpartum follow-up showed consistent plasma glucose at 4.9 mmol/L, a slightly elevated HbA1c at 5.6 %, insulin at 38.54 pmol/L, and C-peptide at 0.42 nmol/L, with no incidents of hypoglycemia reported." (PMID 39100462, 2024). "Hypoglycemia is not uncommon in patients with AUD treated with insulin due to poor nutritional status or impaired liver function, so any blood glucose-lowering prescription should be carefully checked." (PMID 39455970, 2024). "In vivo studies in rats and pigs showed that NNC2215 attenuates hypoglycemia compared to non-glucose-sensitive insulin analogs, such as insulin degludec." (PMID 39766270, 2024). "In a study investigating exenatide’s impact on glycemic variability and hypoglycemia, 30 patients with T1DM were randomly divided into two groups: one received a combination of exenatide (10 μg) and insulin, while the other continued with insulin therapy alone for four weeks." (PMID 39273299, 2024). "Further, the action of WCDD301 during challenging conditions, such as insulin-induced hypoglycemia and dietary or nondietary glycemic volatility, remain to be elucidated." (PMID 38258903, 2024). "Topical insulin has been shown to be superior to autologous serum tears and safe in dosages up to 100 IU/mL of short-acting insulin without any evidence of systemic absorption or hypoglycemia." (PMID 38989397, 2024). "A likely contributor to the reduced variability and/or limited hypoglycemia in those not on insulin therapy is endogenous insulin production that controls excursions and limits large fluctuations in glucose levels." (PMID 38444315, 2024). "In summary, the cumulative effect that a more intensive insulin regimen led to better glucose control without excess hypoglycemia, was confirmed." (PMID 38281042, 2024). "Six participants experienced hypoglycemia (glucose <3.9 mmol/L [<70 mg/dL]) during the control arm, five during the reduced basal insulin infusion rate arm and none during the oral glucose and MDG arms." (PMID 39944479, 2024). "Daily insulin injections, a nutritious diet, and regular physical exercise are the mainstays of achieving optimal glycemic control and avoiding T1DM complications (hypoglycemia, DKA, microvascular and macrovascular complications)." (PMID 39408305, 2024). "In addition to TH, three episodes of insulin-induced hypoglycaemia also increased AADC and PNMT protein expression, while both recurrent glucoprivation and hypoglycaemia increased DBH protein expression within the adrenal gland." (PMID 38392992, 2024). "Nevertheless, evidence is available to confirm insulin's bioavailability and safety profile as systemic adverse events such as hypoglycaemia are non-existent following nasal administration." (PMID 38441832, 2024). "Negative effects were observed for hypoglycemia (β = −1.008), insulin pump use (β = −0.746), and frequent glucose monitoring (β = −0.523)." (PMID 39280993, 2024). "The first generation of insulin pumps that had sensors or sensor-augmented pumps (SAP) were equipped with an insulin shutoff feature that activated if the user did not respond to a hypoglycemia alert." (PMID 39766270, 2024). "In contrast, the percentages of patients receiving sulfonylurea and insulin were higher among patients with hypoglycemia compared with those without hypoglycemia (sulfonylurea 11.1 vs. 1.5%; p = 0.033, insulin 91.7 vs. 60.3%; p = 0.0003)." (PMID 39281187, 2024). "Although he did not have an elevated insulin level, the preponderance of evidence relating to his hypoglycemia was most consistent with hyperinsulinism as the mechanism." (PMID 39659385, 2024).